FOXO3 (forkhead box O3)
Diseases named in the same sentence as FOXO3 in open-access papers (continued):
Sharing a sentence is not in itself a finding about the gene and the disease.
pancreatic cancer (continued). "Each of the fatty acid synthase/Wnt, miR-148a/Wnt10b, Linc00261/miR-552-5p/FOXO3, and miR-454/FAM83A/TSPAN1 axes can be valuable biomarkers and potential therapeutic targets in pancreatic cancer." (PMID 38559560, 2024). "We collected 86 pancreatic carcinoma samples from pancreatic cancer patients and performed tissue microarrays via immunohistochemical staining, to examine the expression of SIRT1, CUL4B, and FOXO3." (PMID 34163012, 2021). "The study substantiated the antitumour activity of LINC00472 in pancreatic cancer and proposed a regulatory axis in which LINC00472 competitively binds to miR‐23a‐3p to enhance the FOXO3 expression and promote BID expression." (PMID 34363438, 2021). "Our study primarily demonstrated the ability of LINC00472 to competitively bind to miR‐23a‐3p to boost the FOXO3 expression and transcriptionally activate the BID expression for suppression of pancreatic cancer progression." (PMID 34363438, 2021). "To evaluate whether the levels of p-AMPK(Thr172) and p-FoxO3(Ser413) are upregulated in skeletal muscle from cancer cachexia patients, we obtained muscle biopsies from cachectic patients affected by malignancies (colorectal and pancreatic cancers) in which cachexia has a 80% prevalence." (PMID 29167426, 2017). "LINC00472 could competitively bind to miR‐23a‐3p to enhance the expression of FOXO3, which consequently could promote the BID expression, thereby suppressing proliferation and promoting the apoptosis of pancreatic cancer cells." (PMID 34363438, 2021). "SIRT1 or CUL4B knockdown in PANC-1 cells decreased cell invasion potential, which was partially rescued via the co-knockdown of FOXO3 or GRHL3, indicating that the SIRT1/CRL4B complex could promote pancreatic cancer invasion through repression of FOXO3 and GRHL3." (PMID 34163012, 2021). "Furthermore, immunohistochemistry and for paraffin-embedded tissue sections and immunofluorescence for the cell lines showed that FOXO3 was localized in the cytoplasm of cells, and the expression of FOXO3 in normal pancreas tissue and HPDE6 was stronger than in pancreatic cancer cells." (PMID 29072689, 2017). "In head and neck squamous cell carcinoma (HNSCC) CSCs, autophagy promotes stemness specifically through a non-canonical FOXO3/SOX2 signaling axis, while in pancreatic cancer stem cells, it contributes predominantly to gemcitabine resistance." (PMID 40886002, 2025). "There was a negative relationship of FOXO3 and β-catenin/TCF4 in pancreatic cancer cells." (PMID 34178644, 2021).
diabetes (50 papers, 2009 to 2025). "In conclusion, the present study extends our findings of an association of protective effects of the G-allele of FOXO3 against diabetes and NAFLD, highlighting its relative importance compared with the well-established risk factors." (PMID 39273459, 2024). "In the search for additional C66-diabetes-associated molecular players, forkhead box O3a (FOXO3a) transcription factor was reported to be an essential downstream signaling effector of apoptosis." (PMID 36316651, 2022). "FOXO3 ameliorates oxidative stress, thereby suppressing renal fibrosis associated with diabetes and hypertension." (PMID 35004893, 2021). "Follow-up until Dec 31, 2019 found that in CMD-affected individuals, longevity-associated alleles of FOXO3 were associated with significantly longer lifespan: haplotype hazard ratio 0.81 (95% CI 0.72-0.91; diabetes 0.77, hypertension 0.82, CHD 0.83)." (PMID 33260156, 2020). "Here we show for the first time that longevity-associated genetic variants of FOXO3 are associated with much lower mortality in elderly individuals who have one or more of the common aging-related conditions consisting of diabetes, CHD and hypertension." (PMID 33260156, 2020). "Hazard ratios (HR) of FOXO3 minor allele carriers vs. major allele homozygotes with total mortality by diabetes, CHD, and hypertension." (PMID 33260156, 2020). "Researchers also demonstrated that miR-182 contributes to the regulation of FOXO3 by targeting FOXO3 in skeletal muscle during chronic diseases (e.g., diabetes, chronic kidney disease) which are associated with elevated glucocorticoid production." (PMID 27999212, 2017). "The future challenge is to test whether rs9486902 in FOXO3 is involved in diabetes and increases susceptibility to diabetes and prediabetes." (PMID 26683100, 2016). "We demonstrated that rs9486902 in FOXO3 gene is associated with human longevity in both genders, and the estimated prevalence of diabetes and prediabetes were significantly lower in long-lived individuals than in common adult population in this Han Chinese population." (PMID 26683100, 2016). "Thereby, we also analyzed whether any of the selected SNPs in FoxO1/FoxO3 is associated with gender, smoking, medical history of hypertension, diabetes mellitus, hyperlipidemia and MetS in our study population." (PMID 24489705, 2014). "Exposure to As through digestion can lead to the development of diabetes via the sirtuin 3 (SIRT3)-forkhead box O3 (FOXO3a) pathway." (PMID 41488239, 2025). "The aim of this study was to investigate the relationship between FOXO3 SNP rs2802292 and diabetes and NAFLD in a previously well-studied large population of middle-aged subjects." (PMID 39273459, 2024). "In pancreatic beta cells, miR-132 controls proliferation and survival through the Pten/Akt/Foxo3 signaling pathway, indicating its involvement in maintaining beta cell function under metabolic stress conditions such as obesity-induced diabetes." (PMID 39195481, 2024). "In this study, for the first time, we observed a relationship between FOXO3 SNP rs2802292 and diabetes and NAFLD in a large population of middle-aged subjects." (PMID 39273459, 2024). "For the gene FOXO3 the protective alleles mitigated the risk of hypertension, coronary heart disease (CHD) and diabetes." (PMID 37561089, 2023). "In fact, pediatric patients with type 1 diabetes mellitus showed significant FOXO3 upregulation, when compared with the healthy controls, suggesting a role of FOXO3 in the development of this disease." (PMID 37891184, 2023). "In this study, we investigate the expression level of FOXO3 in PBMCs from newly diagnosed type 1 diabetes mellitus pediatric patients." (PMID 32851102, 2020).
diabetes (continued). "The regulating Forkhead box O3a (FOXO3a) acetylation by p300 is another mechanism involved in diabetes-induced inflammation: diabetes-induced FOXO3a acetylation prevents its binding to gene target promoters, increasing NOD-, LRR- and pyrin domain-containing protein 3 (NLRP3) inflammasome activation." (PMID 36766773, 2023). "Previous study has revealed that upregulation of FOXO3 may correlate with the pathogenesis of type 1 diabetes mellitus." (PMID 36440209, 2022). "Overexpression of FOXO3 in type 1 diabetes mellitus might suggest a potential role of this gene in the development of autoimmune disease." (PMID 32851102, 2020). "In conclusion, overexpression of FOXO3 is correlated with the ongoing islet autoimmune destruction and might suggest a potential role for this gene in the pathogenesis of type 1 diabetes mellitus." (PMID 32851102, 2020). "Our study found a strong association between diabetes and the non-protective FOXO3 genotype (TT)." (PMID 39273459, 2024). "Moreover, overexpression of FOXO3 was recently shown to be correlated with the destruction of pancreatic islets, which proposes a mechanism through which FOXO3 could contribute to type 1 diabetes mellitus." (PMID 37891184, 2023). "For example, the forkhead box protein O3 gene (FOXO3, OMIM*602681) encoding the IGF-1 pathway downstream transcription factor (TF), forkhead box protein O3 (FOXO3), has been found to be strongly associated with human longevity and the prevalence of diabetes and arterial hypertension." (PMID 36143124, 2022). "ALDH2 overexpression or its agonist Alda-1 improved autophagy to reverse diabetes or high glucose-induced dysfunctions via AMPK and forkhead box O3a (FOXO3a)." (PMID 32116717, 2020). "In stratified analysis according to gender, the history of smoking, hypertension, diabetes mellitus, hyperlipidemia and the metabolic syndrome, we further explored that neither the variants of FoxO1 nor the variants of FoxO3 might be associated with CHD (p>0.05)." (PMID 24489705, 2014). "For FOXO3, MAP3K5, PIK3R1, mitigation of pathological effects of other cardiovascular diseases and/or diabetes represent an additional means whereby individuals with longevity (resilience) genotypes can have a normal lifespan despite possessing one or more of these aging-related conditions." (PMID 37561089, 2023). "In mice, conditional deletion of FoxO1, FoxO3, and FoxO4 was found to affect formation of hematopoietic stem cells and neural stem/progenitor cells, and compromised pancreatic β cell function, leading to maturity-onset diabetes of the young (MODY)-like diabetes." (PMID 37240290, 2023). "Since the lack of Treg-mediated control has fundamental impact on type 1 diabetes mellitus (T1DM) development, we investigated FOXO3 expression in patients with T1DM." (PMID 32851102, 2020).
neuroblastoma (50 papers, 2012 to 2025). Neuroblastoma (NB) is the most common solid, extracranial childhood tumor. "The transcription factor FOXO3 is associated with a poor outcome in high-stage neuroblastoma (NB), facilitating chemoprotection and tumor angiogenesis." (PMID 34572532, 2021). "Our screen identified multiple loci important for Alk signaling, including members of Ras/Raf/ERK-, Pi3K-, and STAT-pathways as well as tailless (tll) and foxo whose orthologues NR2E1/TLX and FOXO3 are transcription factors implicated in human neuroblastoma." (PMID 32917927, 2020). "The transcription factor FOXO3 is associated with poor outcome in high-stage neuroblastoma (NB), as it facilitates chemoprotection and tumor angiogenesis." (PMID 31861249, 2019). "A recent elegant study shows how different neuroblastoma cell lines respond to the activation of an ectopic FOXO3 allele." (PMID 30646603, 2019). "In neuroblastoma cells, FoxO3 has been implicated in sensitization to apoptosis induced by the Top2 inhibitors doxorubicin and etoposide." (PMID 30646603, 2019). "We have shown that FOXO3 causes ROS accumulation, which in turn triggers cell death in neuroblastoma." (PMID 28545464, 2017). "DNA-damaging drugs induced nuclear accumulation of FOXO3, which was associated with elevated T32-phosphorylation in stage IV-derived neuroblastoma cells, thereby reflecting the in situ results." (PMID 27769056, 2016). "In addition, it suppresses FOXO3 transcriptional activity and counteracts FOXO3‐mediated chemoprotection in high‐risk neuroblastoma." (PMID 41002121, 2025). "However, in neuroblastoma cells we observed a different mode of action of Survivin: Survivin mRNA expression is rapidly repressed by FOXO3 and this leads to rapid loss of cytoplasmic Survivin, whereas mitochondrial Survivin shows significantly higher stability." (PMID 23801966, 2013). "The apoptosis of leukemic cells after doxorubicin treatment has already been shown to be dependent upon FOXO3, and in neuroblastoma, FOXO3 sensitizes cells to apoptosis induced through a combination treatment of doxorubicin and etoposide." (PMID 38672531, 2024). "Scientists discovered that the high activation of BIRC5 depressed the respiration of mitochondria and induced its fragmentation, finally led to Foxo3-dependent cell apoptosis by preventing reactive oxygen species accumulation, in neuroblastoma." (PMID 35461228, 2022). "FOXO3 is correlated with a poor outcome in high-stage neuroblastoma due to its’ chemoprotective and angiogenesis-stimulating properties." (PMID 34572532, 2021). "In neuroblastoma, expression of FOXO3 was beneficial as a prognostic marker and a biomarker to assess the efficacy of the PI3K/AKT inhibition." (PMID 34831287, 2021). "Immunofluorescent staining of N2a neuroblastoma and U87 astrocytoma cells showed that, under basal conditions, FoxO3 primarily resided in the cytoplasm, and this pattern was maintained upon insulin treatment." (PMID 34247441, 2021). "In a neuroblastoma model, lumican was a downstream mediator of FOXO3 transcription factor action and enhanced these cells’ migration." (PMID 34572532, 2021). "Recently, several publications identified DEPP as a part of the forkhead box O3 (FOXO3) – reactive oxygen species (ROS) axis that steers cell fate toward either survival or death in the neuroblastoma cell line." (PMID 31963726, 2020). "To verify genome-wide gene expression results we selected four genes previously identified as FOXO3 targets in neuroblastoma cells and evaluated the effect of compound S9 and its oxalate salt S9OX on mRNA expression by quantitative RT-PCR analyses." (PMID 31789593, 2019). "For these experiments the FOXO3-sensitive, high-stage neuroblastoma cell line NB15/FOXO3-GFP was used to directly image cell growth/viability by fluorescence microscopy." (PMID 31789593, 2019).
neuroblastoma (continued). "We previously demonstrated that FOXO3-activation induces a bi-phasic reactive oxygen species (ROS) wave that critically contributes to induction of apoptotic cell death in human neuroblastoma cells." (PMID 31789593, 2019). "To validate these biochemical screening results in living cells we used SH-EP/FOXO3 neuroblastoma cells stably expressing a 4-hydroxy-tamoxifen (4OHT)-regulated FOXO3(A3)ERtm transgene that undergo apoptotic cell death upon activation of FOXO3." (PMID 31789593, 2019). "DEPP1 sensitizes neuroblastoma cells for ROS and is strongly induced by FOXO3 via three functional FOXO consensus sequences in its promoter." (PMID 31789593, 2019). "In a previous report, we demonstrated that DNA-damaging chemotherapeutic agents such as etoposide and doxorubicin activate FOXO3 and thereby induce ROS accumulation and apoptosis in neuroblastoma cells." (PMID 28545464, 2017). "Targeting FOXO3/DEPP-triggered autophagy is a promising strategy to sensitize neuroblastoma cells to chemotherapy." (PMID 28545464, 2017). "The combined data suggest that MG-2477 induces a sequential process of ROS-accumulation, autophagy and FOXO3-activation that leads to cell death in neuroblastoma cells." (PMID 28415610, 2017). "One critical downstream target of the PI3K is the PKB and this survival pathway is frequently hyperactivated in neuroblastoma, which among other targets inactivates the transcription factor FOXO3." (PMID 28415610, 2017). "As a control, we next generated YFP-LC3-expressing neuroblastoma cells with FOXO3 being knocked down by shRNA technology (SH-EP/shFOXO3-16-cl13-YFP-LC3 cells) to monitor autophagosome formation." (PMID 28415610, 2017). "In high-stage neuroblastoma tumors nuclear FOXO3 contributes to death resistance under cellular stress conditions that occur during serum starvation or chemotherapy in the tumor tissue." (PMID 28545464, 2017). "We demonstrated before that FOXO3 induces a biphasic ROS accumulation in neuroblastoma cells, which is significantly reduced by DEPP knockdown due to an increased capacity to detoxify cellular ROS, especially H2O2." (PMID 28545464, 2017). "The combined data suggest that, depending on the mode and intensity of activation, cellular FOXO3 acts as a homeostasis regulator promoting tumor growth at hypoxic conditions and tumor angiogenesis in high-stage neuroblastoma." (PMID 27769056, 2016). "In neuroblastoma cells, the activation of FoxO3 triggers the intrinsic death pathway via induction of Bim and Noxa." (PMID 26405162, 2015). "Taken together, these results demonstrate that DEPP is a transcriptional target of FOXO3 and regulated downstream of insulin-signaling in neuroblastoma cells." (PMID 25261981, 2014). "In neuroblastoma, FOXO3 gets activated as a result of cellular stress response, which leads to cellular ROS formation and upregulation of DEPP expression." (PMID 25261981, 2014). "Propidium iodide-(PI) FACS-analysis showed significantly reduced FOXO3-mediated apoptosis in shRNA-expressing neuroblastoma cell lines." (PMID 25261981, 2014). "In neuroblastoma cells, FOXO3 regulates cellular apoptosis by activating the two BH3-only proteins PMAIP1/Noxa and BCL2L11/Bim and sensitizes these tumor cells to chemotherapy-induced cell death by repressing the IAP-family member BIRC5/Survivin." (PMID 25261981, 2014). "In the present study we investigated the regulation of DEPP by FOXO3 in human neuroblastoma cells and addressed its effects on cellular ROS household and tumor growth." (PMID 25261981, 2014). "In this study we demonstrate for the first time that the FOXO3-regulated gene DEPP impairs ROS detoxification via the enzyme catalase and thereby increases the effects of ROS on FOXO3-induced apoptosis in neuroblastoma cells." (PMID 25261981, 2014). "In SH-EP neuroblastoma cells the PI3K-PKB signaling pathway is highly active, which causes cytoplasmic retention of FOXO3." (PMID 23801966, 2013).